TNF (tumor necrosis factor)
Diseases named in the same sentence as TNF in open-access papers (continued):
Sharing a sentence is not in itself a finding about the gene and the disease.
malaria (continued). "Although a previous study reported co-expression of TNF and IL6 by IL-10 producing Bregs138, only a small fraction of IL-10+ Bregs co-produced IL6 during malaria, and there was minimal co-expression with TNF." (PMID 37968278, 2023). "Increased TNF, IFN-γ, IL-6, IL-10, IL-17, CCL2, and CCL3 levels and decreased IL-7 levels were observed in malaria monoinfection compared to dengue virus monoinfection." (PMID 36716305, 2023). "Malaria infected individuals produce varying levels of TNF-α; the level of TNF-α production is directly proportional to malaria severity." (PMID 37215099, 2023). "Distinct cytokine profiles in malaria and HIV coinfections compared to malaria monoinfections were increased IL-12, CXCL9, CXCL11, IL-18, and G-CSF levels and decreased TNF and IL-4 levels." (PMID 36716305, 2023). "Activation of monocytes by IFN-γ results in classical activation of macrophages, leading to the release of pro-inflammatory cytokines such as IL-6 and TNF-α, and increased concentration of IFN-γ has been observed during both babesiosis and malaria." (PMID 36839438, 2023). "The increased IL-12 levels in patients with uncomplicated malaria were related to the increased TNF-α levels; TNF-α is an essential cofactor for IL-12 that induces the NK cells to produce interferon γ." (PMID 35954703, 2022). "Immune-related genes TLR2 in Malaria and Legionellosis and IL-18 and IL18R1 in the TNF signaling pathway were upregulated in the LG compared to in the BG (p < 0.05)." (PMID 35268235, 2022). "Most of the pathways of this cluster (TNF, PI3K, MAPK, malaria, amoebiasis, and others) predominantly translated signals of inflammatory and immune responses." (PMID 36553646, 2022). "In mouse models of liver-stage malaria, there is a distinct increase in IL-4, IL-10, TGF-β, and downregulation of IFN-γ, IL-12, and TNFα." (PMID 36415655, 2022). "TLR2 in Malaria and Legionellosis and IL-18 and IL18R1 in the TNF signaling pathway were upregulated in the LG compared to in the BG (p < 0.05)." (PMID 35268235, 2022). "IL-6, IL-13, TNF-α, and IFN-γ were significantly higher in severe malaria, while IL-7, IL-10, IL-17, and IL-27 showed the opposite trend." (PMID 36293524, 2022). "KEGG pathway enrichment results showed that the DEGs were significantly centralized at “Malaria”, “Proteoglycans in cancer”, “ECM-receptor interaction” and “TNF signaling pathway”." (PMID 35036156, 2021). "Asymptomatic malaria is characterized by increased Treg numbers, IL-10 and TGF-β production, and dampened TNF, IFN-γ pro-inflammatory response characterizes." (PMID 33746974, 2021). "Patients with bacteremia had lower circulating IL-10, TNF-α and IFN-γ and higher IL-6 concentrations, compared to clinical malaria." (PMID 34177883, 2021). "It has also been found that individuals with greater malaria disease severity had higher levels of CRP, TNFα, and IFNg." (PMID 33731158, 2021). "Significantly lower cytokine responses (IL-1β, IL-6, IL-10, TNF-α and IFN-γ) to LPS and Staphylococcus aureus were observed among participants with asymptomatic malaria compared to controls." (PMID 34177883, 2021). "Thus, elevated TNF-α levels may serve as specific indicator for aberrant inflammatory responses in Malaria patients, particularly in individuals infected with P. falciparum, that have increased risk for deregulated EBV homeostasis and subsequent risk of developing EBV-related disease." (PMID 34962938, 2021). "Several of these cytokines, such as TNF-α and IFN-γ play a protective role in malaria by arresting parasite replication and enhancing parasite killing, but also contribute to anemia by inhibiting erythropoiesis." (PMID 32373101, 2020). "While redundant, our data indicate that in these malaria models the mechanism by which caspases-1/11 promotes IL-1β release involves GSDM-D, whereas caspase-8 seems to mediate expression of pro-IL-1β and TNFα." (PMID 32929083, 2020).
malaria (continued). "The present study showed that serum levels of IL- 6, TNF-α, and IFN-γ were significantly elevated in HIV seropositive pregnant participants with malaria coinfection." (PMID 33193759, 2020). "HIV-malaria coinfected pregnant women showed significantly higher levels of IL-6, IFN-γ, TNF-α, and blood pressure with reduced BMI value compared with HIV seronegative pregnant and nonpregnant control participants (p ≤ 0.001, respectively)." (PMID 33193759, 2020). "The results indicate that differential expression of CXCL10, TNF-α, CCL2, IL-8, and IL-6 were tightly linked to hemoglobin genotype and severity of Plasmodium infection and that these cytokine levels may be predictive for susceptibility to severe malaria or SCD severity." (PMID 33424841, 2020). "Levels of circulating pro- (IL-6, TNF-α and IFN- Υ) and anti-inflammatory cytokines (IL-10) were highest in clinical malaria." (PMID 33253198, 2020). "There is a strong relationship between the anthropometric indices (SBP and BMI) and cytokines (TNF-α and IFN-ṿ) in HIV seropositive pregnant women with malaria coinfection." (PMID 33193759, 2020). "However, the precise mechanisms by which TNF is involved in severe malaria remains unknown." (PMID 31871954, 2019). "Cases with HAT and/or malaria parasites responded with an overall increase in secretion of pro-inflammatory cytokines (IFN-γ and TNF-α), which partially suggested the effect induced by either HAT or malaria mono-infections." (PMID 31687034, 2019). "Accordingly, it was reported that TNF2 allele (-308, aka rs1800629) controlled elevation of serum TNF in severe malaria patients but not in patients with uncomplicated malaria suggesting that its capacity to control gene expression may be modified in the course of infection." (PMID 31417551, 2019). "Patients with malaria-HBV coinfection presented elevated concentrations of multiple variables such as IFN-γ, TNF-α, IL-4, IL-10, CCL2, and reduced levels of IL-12 and creatinine levels when compared to those with asymptomatic vivax malaria monoinfection." (PMID 31233500, 2019). "The assay was carried out for five plasma cytokines (IFN-γ, TNF-α, IL-6, IL-10, and TGF-β) in HAT and/or malaria cases and healthy controls." (PMID 31687034, 2019). "Studies in malaria patients identified monocytes, particularly CD14+CD16+ inflammatory monocytes, and γδ T cells, as the main cellular sources of TNF." (PMID 30239833, 2019). "Malaria and HAT co-infection modified synergistically the pro-inflammatory (IFN-γ, TNF-α) and anti-inflammatory (IL-6, and IL-10) cytokine response than P. falciparum mono-infections." (PMID 31687034, 2019). "In malaria studies, certain receptors and cytokines are commonly investigated, such as CD163, IL-10, and TNF." (PMID 31662766, 2019). "Malaria and/or HAT cases presented significant higher plasma cytokine levels of IFN-γ, TNF-α, IL-6, IL-10 and TGF-β than healthy controls (P < 0.05)." (PMID 31687034, 2019). "While peripheral levels of TNF-α, IL-1β and IL-6 were similar in women with Malaria and CHB, the pro-inflammatory cytokines were significantly increased in those with Malaria+CHB, which further suggests a possible additive effect of the infections." (PMID 31002731, 2019). "It has been reported that the immune system of the shark offers a good antibody response against different proteins such as: HEL, Ebolavirus nucleoprotein, TNFα, ICOSL, VEGF, malaria PfHRP2, amongst others." (PMID 31206542, 2019). "PD-1 expression on parasite-specific CD4+ cells results in a reduction in proliferation, as well as IFN-γ and tumor necrosis factor alpha (TNF-α) secretion, during the chronic phase of malaria." (PMID 31711531, 2019). "The TNF-α plasma level partially indicated the effect induced by mono-infections of HAT and malaria or from a synergistic effect of the co-infection which indicates a protective immunity against the parasites." (PMID 31687034, 2019).
malaria (continued). "Some cytokines and chemokines (such as TNF and MIP-1β/1α) which increase the risks of severe malaria, however, are derived from γδ T cell." (PMID 30116753, 2018). "In fact, antigen-specific T cells defined by CD40L expression that were also producing TNFα or IL2 induced by RTS,S/AS vaccination were higher in individuals protected from malaria." (PMID 30065162, 2018). "In AD-specific AD_M22, genes are enriched in legionellosis, TNF signaling pathway, salmonella infection, chemokine signaling pathway, NOD-like receptor signaling pathway, malaria, AGE-RAGE signaling pathway, and amoebiasis." (PMID 30598117, 2018). "Murine models of malaria demonstrate a regulation of balance between IL-10 and inflammatory cytokines such as IFN-γ and TNF-α." (PMID 29970128, 2018). "Severe malaria patients display increase levels of pro-inflammatory cytokines, TNF, IL-6 and IFN-γ while acute malaria individuals show high levels of the anti-inflammatory cytokines IL10." (PMID 28288644, 2017). "Our data suggest opposing roles for TNFα and IL10 Pf-specific CD4 T cells in naturally acquired immunity to malaria in children." (PMID 29097996, 2017). "IL-12 has been shown to be involved in protective immunity against malaria by regulating IFN-γ, TNF-α, and nitric oxide responses in experimental studies and enhancing erythropoiesis in Plasmodium chabaudi-infected susceptible mice." (PMID 28122790, 2017). "According to this study, IFN-γ, IL-2, IL-5, IL-6 and IL-12 were increased in mild malaria whereas TGF-β, TNF, IL-10 and IL-1β were particularly elevated in CM." (PMID 28775960, 2017). "Intracellular cytokine production (IFN-γ, TNFα, IL2, and IL17A) from PBMC stimulated with pooled malaria and schistosoma antigens was measured in 24 SP Mal and 24 SN Mal children (n = 48)." (PMID 29449839, 2017). "The network of biomarkers in patients suffering mild malaria consisted of IFN-γ, tumor necrosis factor (TNF), and chemokine (C–C motif) ligand 5, while the interaction occurred between CXCL9 and IL-12 in symptomatic patients." (PMID 28243235, 2017). "Plasma levels of inflammatory cytokines (IFNα, IFNγ, TNF, IL-6) and chemokines (CCL2, CCL3, CCL4, CXCL10) were significantly higher during severe malaria compared to convalescence." (PMID 27792766, 2016). "Factors associated with severe malaria that may be affected by hydroxyurea in children with SCA include intracellular adhesion molecule-1 (ICAM-1), vascular cellular adhesion molecule-1 (VCAM-1), von Willebrand factor (VWF), tumor necrosis factor-alpha (TNF-α), and nitric oxide (NO)." (PMID 27339303, 2016). "Given our findings on the heme/hemopexin balance that influences cytokine profiles during severe malaria, we first investigated a possible correlation between EPO, TNF-α, IL-10, IP-10 and MCP-1 plasma levels." (PMID 27441662, 2016). "Cytokines such as TNF, IFN-γ and IL-10 participate in cellular and humoral immune modulation in malaria and affect pathogenesis, parasitaemia control and pathophysiology, which are dependent on the cellular and circulating levels of these cytokines." (PMID 27435973, 2016). "High ratios of TNFα and INFγ levels to IL10 or TGFβ levels have also been observed in other studies in patients with severe malaria." (PMID 27802341, 2016). "In severe malaria, there is an increased level of inflammatory cytokines, such as interferon gamma (IFN-γ, tumor necrosis factor alpha (TNF- α and interleukin (IL)-6." (PMID 26943639, 2016). "In order to demonstrate the role of cytokines in the modulation of HAT progression, we assayed six cytokines (IFN-γ, IL1-β, TNF-α, IL-6, TGF-β and IL-10) in plasma of both cases (N = 49, after excluding 6 malaria co-infected patients) and controls (N = 41)." (PMID 26090964, 2015). "Plasma levels of pro-inflammatory (TNF-α and IFN-γ) and anti-inflammatory (IL-10) cytokines known to be involved in both pathogenesis and defence mechanisms against malaria were also measured." (PMID 26178656, 2015).
malaria (continued). "Thus, the absence of malaria-specific CD4+ T cells producing TNFα may be associated with the phenotype of asymptomatic infection." (PMID 24415936, 2014). "Also, TRPV1 effects on TNFα production may vary at different stages of malaria." (PMID 25242870, 2014). "The first aim of this study was to examine TNF and IFN-γ cytokine concentrations in pregnant women with a clinical diagnosis of malaria." (PMID 25124540, 2014). "Similar findings were obtained when analyzing the “composition” (i.e. the proportion of responding cells producing IFNγ, TNFα, and/or IL10) of the malaria-specific response and duration since last malaria infection." (PMID 24415936, 2014). "Studies in mice infected with Plasmodium chabaudi malaria have shown that IFN-γ and TNF-α cooperatively induce nitric oxide synthase expression in the spleen to control peak parasite burden." (PMID 24904561, 2014). "For example, in malaria, activation of MMP-9 was dependent upon the production of TNF and its activation was decrease by anti-TNF treatment." (PMID 25393535, 2014). "IL-1 acts synergistically with TNF-α to enhance NO and IFN-γ production in murine models of malaria." (PMID 24130857, 2013). "Plasma endotoxin levels in severe malaria negatively correlated with IL6, IL10 and TGFβ (Spearman rho: TNFα: r= −0.122, p=0.121; IL6: r=−0.330, p<0.0001; IL10: r=−0.461, p<0.0001; TGFβ: r=−0.173, p<0.027)." (PMID 23497104, 2013). "After evaluating the cytokine profile (IL-2, IL-4, IL-6, IL-10, TNF-α, IFN-γ and IL-17) in the patients’ sera, levels of IL-6, IL-10 and IFN-γ were elevated in malaria patients compared to HV." (PMID 23723981, 2013). "In parallel, the secretion of tumor necrosis factor-alpha (TNF-α) appears to induce oxidative stress through modulation of GSH metabolism, playing an important role in malaria physiopathogenesis." (PMID 23208374, 2012). "There is less field data available on the relevance of individual cytokines in naturally acquired immunity to malaria, e.g. IL-12, IFN-γ, TNF, or IL-10." (PMID 22280502, 2012). "Similar observations have been reported where malaria patients responded to P. falciparum infected erythrocytes with significant increases in the percentage of IL-2, IFN-γ, and TNF, but also IL-10, positive cells." (PMID 22280502, 2012). "We also show that IFNγ-IL2+TNF−, IFNγ-IL2+TNF+, and IFNγ-IL2-TNF+ CD4+ T cells were induced by natural exposure to malaria in the control vaccinees." (PMID 23300801, 2012). "We find that vaccination of malaria-exposed children with RTS,S/AS01E induces IFNγ-IL2+TNF− and IFNγ-IL2+TNF+ CD4+ T cell responses upon in vitro stimulation of whole blood with CSP peptides." (PMID 23300801, 2012). "In contrast, for the malaria infected, BCG vaccinated mice, the TNF-α MFI values of CD4 T cells were strikingly reduced in IFN-γ/TNF-α (70% reduction) and triple positive cells (89%) relative to controls not infected with P. yoelii." (PMID 22205939, 2011). "Hence, while neither CD4+ TNFα+ cells nor anti-CS antibodies alone accounted for all of the effect of vaccination with RTS,S/AS01E on clinical malaria risk, the combination of CD4+ TNFα+ T cells and anti-CS antibodies together could account for all of the statistical effect of vaccination." (PMID 21998698, 2011). "Both in human and experimental malaria, enhanced TLR activation is suggested to prime proinflammatory cytokine responses (IL-12, IFN-γ, TNF-α), which in turn can favor host hyperresponsiveness to TLR agonists during acute malaria." (PMID 22096530, 2011). "In summary, in early P. chabaudi malaria, IFN-γ and TNF-α production by spleen cells is intense, short-lasting and mostly dependent on conventional CD4+ T cells." (PMID 21814579, 2011). "The malaria pigment hemozoin has been proposed as a novel TLR-9 ligand, inducing TNF, IL-6 and IL-12 p40 production, but it has subsequently been suggested that contaminating malarial DNA, which binds to hemozoin, is responsible for TLR-9 activation." (PMID 20126448, 2010).
malaria (continued). "With this limited sample size, the finding of the lack of association between malaria disease pathogenicity/severity genetic polymorphisms of HO-1 (GT)n repeat as well as TNF observed in this study may not entirely exclude their possible link with malaria disease pathogenicity/severity." (PMID 20846452, 2010). "Schistosoma haematobium infection was shown to reduce malaria severity by increasing Th2 responses in P. falciparum-infected children; a recent ex-vivo study indicates that helminth infections cause an increase in IL-10 but no change in TNF, indicating suppression of pro-inflammatory responses." (PMID 20051114, 2010). "Blood samples were collected from 329 cases non-severe malaria with acute uncomplicated Plasmodium falciparum malaria (UM) and 80 cases with Plasmodium vivax malaria (VM), and 77 cases with severe or cerebral malaria (SM) for analysis of genetic polymorphisms of HO-1 and TNF and cadmium levels." (PMID 20846452, 2010). "The defense/immune response interactome is structured around three hubs of high interconnectivity–TNF, IFN-γ and IL-6, all of which play significant roles in host pro-inflammatory responses to malaria." (PMID 18483551, 2008). "Furthermore, we propose that TNF-α and other proinflammatory factors which are activated following the release of malaria antigens after schizont rupture may induce the local production of IP-10 by the constituent cells of the BBB (glial cells, astrocytes, and endothelial cells)." (PMID 17997848, 2007). "Like TNF, HMGB1 has roles in other inflammatory diseases, reaffirming malaria's position within their ranks." (PMID 17029647, 2006). "Elevated levels of adipsin, C3a, C5a, TNF‐α and IL‐8 were found in both preeclamptic groups (with and without malaria) and the normotensive group with malaria compared with the controls." (PMID 41536443, 2026). "Furthermore, frequencies of atypical MBCs had a positive correlation with serum concentrations of the proinflammatory cytokines tumor necrosis factor (TNF) and interleukin (IL)-8 in a cohort with a lifelong exposure to malaria." (PMID 40321757, 2025). "Consistent with this link, Vδ2+ γδ T cells from malaria-naive adults have higher frequencies of IFNγ and TNF-producing cells in response to malaria in vitro stimulation compared to children and circulating CXCL9 was correlated with age in patients with malaria." (PMID 41027884, 2025). "For instance, in severe malaria, elevated levels of IFN-γ and TNF-α, along with the upregulation of TGF-β mRNA, have been shown to cause downregulation of IL-12α and IL-2 levels, suggesting potential dysregulation of the cytokine network through T cell suppression." (PMID 41194029, 2025). "Our findings revealed a significant elevation in IL-1β, but not TNF-α, in mice with tumors and treated with chloroquine, in mice infected with Plasmodium berghei, and in mice with tumors and healed of malaria." (PMID 38774541, 2024). "Severe malarial anemic children had elevated TNF‐α (p < .001), IFN‐ɣ (p < .001), IL‐1β (p < .001), IL‐6 (p < .001), GM‐CSF (p < .001), and IL‐10 (p < .001), but lower IL‐3 (p < .001) and TGF‐β (p < .001) than those with uncomplicated malaria." (PMID 39240033, 2024). "Mice with tumors showed a significant increase in serum levels of IL-1β but not TNF-α when treated with chloroquine, infected with malaria, or healed of malaria." (PMID 38774541, 2024). "Malaria coinfections with bacteremia were characterized by distinct cytokine profiles, including elevated IFN-γ, IFN-α, IL-4, IL-7, IL-12, IL-15, and IL-17 levels and decreased TNF levels, indicating a strong cytokine response." (PMID 36716305, 2023). "While ex vivo IFNγ expression was below the limit of detection for all NK cell subsets, there was a significant increase in TNF production in Adaptive, but not CD56bright NK cells during malaria." (PMID 37968278, 2023).